RICTOR (RPTOR independent companion of MTOR complex 2)
Description:
Component of the mechanistic target of rapamycin complex 2 (mTORC2), which transduces signals from growth factors to pathways involved in proliferation, cytoskeletal organization, lipogenesis and anabolic output. In response to growth factors, mTORC2 phosphorylates and activates AGC protein kinase family members, including AKT (AKT1, AKT2 and AKT3), PKC (PRKCA, PRKCB and PRKCE) and SGK1. In contrast to mTORC1, mTORC2 is nutrient-insensitive. Within the mTORC2 complex, RICTOR probably acts as a molecular adapter. RICTOR is responsible for the FKBP12-rapamycin-insensitivity of mTORC2. mTORC2 plays a critical role in AKT1 activation by mediating phosphorylation of different sites depending on the context, such as 'Thr-450', 'Ser-473', 'Ser-477' or 'Thr-479', facilitating the phosphorylation of the activation loop of AKT1 on 'Thr-308' by PDPK1/PDK1 which is a prerequisite for full activation. mTORC2 catalyzes the phosphorylation of SGK1 at 'Ser-422' and of PRKCA on 'Ser-657' (By similarity). The mTORC2 complex also phosphorylates various proteins involved in insulin signaling, such as FBXW8 and IGF2BP1 (By similarity). mTORC2 acts upstream of Rho GTPases to regulate the actin cytoskeleton, probably by activating one or more Rho-type guanine nucleotide exchange factors. mTORC2 promotes the serum-induced formation of stress-fibers or F-actin.
Synonyms: hAVO3; KIAA1999; MGC39830; AVO3; PIA
Tractability: Small molecule: a structure with a bound ligand is known; a high-quality ligand is known. Antibody: UniProt places it where antibodies can reach, with high confidence; its Gene Ontology location is reachable by antibodies, with high confidence. PROTAC: UniProt records ubiquitination sites on it; ubiquitination databases record sites on it; its protein half-life has been measured; a small molecule that binds it is known.
Target class: Other cytosolic protein
Gene: Protein-coding gene on chromosome 5 (38,937,920 to 39,074,402, reverse strand). Ensembl gene ENSG00000164327.
Subcellular location: Cell membrane; Endoplasmic reticulum membrane; Lysosome membrane
Subcellular location (Human Protein Atlas): Mitochondria
Pathways (Reactome):
Disease: Constitutive Signaling by AKT1 E17K in Cancer; Dengue virus modulates apoptosis
Signal Transduction: PIP3 activates AKT signaling; VEGFR2 mediated vascular permeability
Cellular responses to stimuli: High laminar flow shear stress activates signaling by PIEZO1 and PECAM1:CDH5:KDR in endothelial cells
Immune System: CD28 dependent PI3K/Akt signaling
Gene Ontology:
Molecular function: ATP binding; enzyme-substrate adaptor activity; molecular adaptor activity; protein binding; protein kinase binding; protein serine/threonine kinase activator activity; protein serine/threonine kinase activity; ribosome binding; zinc ion binding
Biological process: actin cytoskeleton organization; positive regulation of cell migration; positive regulation of phosphatidylinositol 3-kinase/protein kinase B signal transduction; positive regulation of TOR signaling; regulation of actin cytoskeleton organization; regulation of phosphatidylinositol 3-kinase/protein kinase B signal transduction; TORC2 signaling; cellular response to nutrient levels; cytoskeleton organization; embryo development ending in birth or egg hatching; lipid biosynthetic process; negative regulation of apoptotic process; positive regulation of cell growth; positive regulation of endothelial cell proliferation; TOR signaling
Cellular component: endoplasmic reticulum; endoplasmic reticulum membrane; lysosomal membrane; lysosome; plasma membrane; TORC2 complex; cytosol; Golgi apparatus
Genetic constraint (gnomAD): Loss-of-function variants: 15 observed, 75.7 expected, observed/expected ratio (o/e) 0.2, 90% interval 0.13 to 0.31. The upper end of that interval is the gene's LOEUF score, 0.31, which puts it in group 1 of 6, group 1 being the genes least tolerant of losing a copy. Missense variants: 778 observed, 1,016.2 expected, observed/expected ratio (o/e) 0.77, 90% interval 0.72 to 0.81. Synonymous variants: 373 observed, 364.04 expected, observed/expected ratio (o/e) 1.02, 90% interval 0.94 to 1.12.
Cancer hallmarks: angiogenesis (promotes); invasion and metastasis (promotes); change of cellular energetics (promotes); escaping programmed cell death (promotes); proliferative signalling (promotes); escaping immune response to cancer (promotes)
Homologues: Orthologues: chimpanzee RICTOR (99% identical), macaque RICTOR (99% identical), dog RICTOR (98% identical), pig RICTOR (98% identical), rabbit RICTOR (98% identical), rat Rictor (97% identical), mouse Rictor (95% identical), guinea pig RICTOR (84% identical), tropical clawed frog rictor (81% identical), zebrafish rictorb (74% identical), zebrafish rictora (72% identical), Drosophila melanogaster rictor (29% identical), and 1 more.
Diseases named in the same sentence as RICTOR in open-access papers:
RICTOR is named in the same sentence as 130 diseases in open-access papers, as found by Europe PMC text mining. Sharing a sentence is not in itself a finding about the gene and the disease. The quoted sentences say what the papers report.
breast carcinoma (23 papers, 2015 to 2025). "RICTOR expression has been reported to be upregulated in invasive and high-grade breast cancers, supporting Akt-mediated survival, while loss of mTORC2 has been shown to enhance apoptosis." (PMID 41300329, 2025). "Considering the plasticity of cells between naïve MSCs and breast cancer cells, the higher mutational frequency of RICTOR may be related to the bone tropism of MBC cells." (PMID 34272397, 2021). "In each dataset, tumor RICTOR amplification/overexpression correlated with a decreased patient OS, consistent with previous reports correlating RICTOR mRNA expression with decreased survival in patients with breast cancer." (PMID 40019775, 2025). "In the context of TNBC, meta-analyses of clinical breast cancer expression datasets revealed that high RICTOR expression correlated with decreased progression-free survival in basal-like 1 and basal-like 2 TNBC subtypes." (PMID 40019775, 2025). "Here, we show that RICTOR, the regulatory subunit of mTORC2, regulates the synthesis of sphingolipids and gangliosides in human luminal breast cancer-specific MCF-7 and BT-474 cells through transcriptional and epigenetic mechanisms." (PMID 40934285, 2025). "In many cancers, including Cervical and Breast cancer, RICTOR overexpression leads to increased Akt S473 phosphorylation and promotes tumorigenesis." (PMID 37372460, 2023). "In breast cancer cells, Pk1 interacts with Mink1 and RICTOR to engage Akt signaling-mediated reorganization of the actin cytoskeleton to promotes breast cancer cell migration." (PMID 35646914, 2022). "Targeting of mTORC2 either by kinase inhibitors or RICTOR knockdown induces apoptosis of breast cancer cells and suppresses cell migration and metastasis." (PMID 35250965, 2021). "RICTOR upregulation was found to be contributed to the hyperactivation of Akt, aggressive breast cancers, and decreased overall survival." (PMID 35250965, 2021). "In breast cancers, RICTOR was enriched in HER2-amplified samples and correlated with increased phosphorylation of AKT at S473, consistent with a potential role for mTORC2 in HER2-amplified breast cancers." (PMID 29455662, 2018). "The importance of the PI3K/AKT signaling is well documented in HER2-amplified breast cancer models and the role of RICTOR/mTORC2 is becoming increasingly recognized." (PMID 29455662, 2018). "RICTOR/mTORC2 has also been found essential for the ability of HRG (EGF-like growth factor) to promote transformation of HRG-sensitive breast cancer cells." (PMID 29455662, 2018). "It has been shown that the adaptor PRICKLE1 interacts with RICTOR, controls actin cytosqueleton organization and contributes to breast cancer cells dissemination." (PMID 29455662, 2018). "Computationally, PTPRF, PRKAR2B, MAP4K3, and RICTOR were calculated as highly drug-targetable genes for breast cancer." (PMID 26336805, 2015). "We report that gene amplification or overexpression of the mTORC2-required cofactor RICTOR correlated with increased mTORC2 signaling and worse patient outcomes in clinical breast cancer expression datasets, supporting studies examining selective mTORC2 inhibition in TNBC." (PMID 40019775, 2025). "In addition, RICTOR knockdown reduced cellular chemotactic capacity and ablates pulmonary metastasis in breast cancer." (PMID 35096817, 2021). "Finally, gene network analysis revealed that p52SHC KO disrupted multiple key pathways that have been previously implicated in breast cancer initiation and progression, including ESR1 and mTORC2/RICTOR." (PMID 31202267, 2019).
breast carcinoma (continued). "The incorporation of metrics such as status of BRCA1, RICTOR, and activation of mTORC2 could guide patient selection for personalized therapies that may significantly increase the survival of breast cancer patients." (PMID 31771139, 2019). "Besides lung cancer, ESCC, melanoma, GC and breast cancer, RICTOR overexpression was also reported in glioblastoma, hepatocellular carcinomas and pancreatic ductal adenocarcinoma (PDAC)." (PMID 29455662, 2018). "Moreover, inhibition of RICTOR or PTPRF was expected to prolong lifespan of breast cancer patients according to patient information annotated in microarray data." (PMID 26336805, 2015). "In line with our findings in human cell culture and mouse models, we observe an elevated expression of RICTOR, ZFX, and UGCG in Indian luminal breast cancer tissues and in TCGA and METABRIC datasets." (PMID 40934285, 2025). "To assess the correlation of RICTOR, UGCG, and ZFX in cancer cells, we analyzed publicly available single-cell RNA sequencing datasets from breast cancer patients (GSE176078)." (PMID 40934285, 2025). "Together, we establish a key regulatory circuit, RICTOR-AKT-ZFX-UGCG-Ganglioside-EGFR-AKT, and elucidate its contribution to breast cancer progression." (PMID 40934285, 2025). "Therefore, we hypothesized that RICTOR (mTORC2) might regulate the sphingolipid metabolism, and increased levels of glucosylceramides may be instrumental for enhanced cancer cell proliferation and tumor progression in luminal breast cancer patients." (PMID 40934285, 2025). "Here, we show that AKT/RICTOR-mediated epigenomic alterations in DNA and histone methylation lead to the rewiring of UGCG transcriptional competence in luminal breast cancer (MCF-7 and BT-474) cells." (PMID 40934285, 2025). "Here, we functionally characterized and defined important functions for mTORC2/RICTOR and GATOR2/WDR59 in controlling mammary tumor growth in TNBC." (PMID 34031411, 2021). "Strikingly, individual RICTOR and WDR59 genomic deletion significantly blocked primary mammary tumor growth and reduced tumor size in NSG mice, highlighting these two proteins as potent pro-oncogenic factors." (PMID 34031411, 2021). "ILK in complex with RICTOR phosphorylates the Ser473 residue of AKT in MDA-MB-231 and MDA-MB-468 breast cancer cells and PC3 prostate cancer cells, where it promotes cell survival and invasion independent of mTORC2." (PMID 28082369, 2017). "Several previous studies investigated RICTOR and MAP4K3, both of which are our proposed drug targets for breast cancer." (PMID 26336805, 2015). "This study shows that RICTOR, the regulatory subunit of mTORC2, regulates the synthesis of sphingolipids and gangliosides by modulating the expression of the UGCG enzyme, thereby promoting breast cancer growth." (PMID 40934285, 2025). "In breast cancer, MMP2 and MMP9 were determined as important downstream effectors of PI3K/AKT signaling and MMP2 was shown to be activated by PI3K/AKT, regulated by RICTOR for the vasculogenic mimicry of tumor cells." (PMID 35096817, 2021). "Importantly, activation of both RICTOR and WDR59 gene expression led to a significant increase in mammary tumor growth." (PMID 34031411, 2021). "Additionally, ablation of RICTOR/mTORC2 signaling subsequent RICTOR knockdown or treatment with mTORC1/2 dual kinase reduced Akt-mediated tumor cell survival and promoted lapatinib-mediated cell killing in HER2+ breast cancer cells, a dual HER2/EGFR tyrosine kinase inhibitor." (PMID 35250965, 2021). "Our study also revealed multiple PAM signaling components as important regulators of the tumorigenic process, further defining roles for mTORC2/RICTOR and GATOR2/WDR59 in TNBC mammary tumor growth and suggesting that Sestrin3-mediated negative regulation of GATOR2 may prevent these effects." (PMID 34031411, 2021).
hepatocellular carcinoma (12 papers, 2017 to 2025). A malignant tumor that arises from hepatocytes. "Interestingly, overexpression of RICTOR was positively associated with tumor progression and poor survival in colorectal cancer, hepatocellular carcinoma, endometrial carcinoma, pituitary adenoma and PDAC." (PMID 29455662, 2018). "FOXD3-AS1 promotes the invasion and migration of hepatocellular carcinoma Huh6 cells by serving as a miR-335 sponge, enhancing RICTOR expression and activating the AKT signaling pathway." (PMID 35280790, 2022). "Overexpression of RICTOR has been reported in several tumor entities including colorectal cancer, gastric cancer and hepatocellular carcinoma (HCC)." (PMID 28445935, 2017). "In hepatocellular carcinoma (HCC), the competitive binding of high-mobility group box 1 (HMGB1) and RICTOR in the mTOR pathway to miR-200 family members, such as miR-429, supports tumor self-renewal, tumorigenesis, and glutamine metabolism." (PMID 39724442, 2024). "In hepatocellular carcinoma, FOXD3-AS1 improves the expression of RICTOR and activates AKT signaling through an interaction with miR-335, thus exerting a pro-proliferative function in Huh6 cells." (PMID 35280790, 2022). "When come to hepatocellular carcinoma, the relationship of FOXD3-AS1, miR-335, and RICTOR can explain the mechanism of tumorigenesis and progression." (PMID 34395290, 2021). "In a study on hepatocellular carcinoma (HCC), the high-mobility group box 1 gene (HMGB1) and the important molecule RICTOR in the mTOR pathway competitively bound to members of the miR-200 family, especially miR-429." (PMID 38302430, 2024).
lung carcinoma (12 papers, 2017 to 2024). "We found that LUAD and LUSC have higher mRNA expression when comparing mutated and wild-type tissue, indicating mutation is one of the main reasons of RICTOR abnormal expression in lung cancer." (PMID 37372460, 2023). "We have recently identified new tumor types with RICTOR (rapamycin-insensitive companion of mTOR) amplification and associated mTORC2 hyperactivity as useful potential targets for developing targeted therapies in lung cancer and other newly described malignancies." (PMID 38515456, 2024). "Selective RICTOR or mTOR2 inhibitors have not been developed, but mTOR1/2 inhibitors have shown good therapeutic activity in RICTOR-amplified lung cancer cells." (PMID 36909198, 2023). "As expected, KM plotter analysis showed that lung cancer patients who highly expressed ERK, AKT, c-myc, 4EBP1, RPTOR (regulatory associated protein of mTOR complex 1) and RICTOR (RPTOR independent companion of mTOR complex 2) has a shorter survival time." (PMID 34421360, 2021). "Its oncogenic roles were suggested by decreased lung cancer cell growth both in vitro and in vivo with RICTOR ablation, and the capacity of RICTOR to transform Ba/F3-cell." (PMID 29455662, 2018). "A study of 640 patients with metastatic solid tumors (primarily gastrointestinal and lung cancers) confirms the amplification of RICTOR in lung cancer and demonstrated that RICTOR amplification was rare but recurrent in gastric cancer (GC)." (PMID 29455662, 2018). "YY1, RTN4, RICTOR, SFPQ, LARP6, and HELLS have been associated with cancers previously and, in this study, exhibited differential level changes between control, Idiopathic Pulmonary Fibrosis (IPF) and lung cancer cells." (PMID 37569873, 2023). "Lung cancer cells with RICTOR amplification showed increased sensitivity to mTORC1/2 inhibitors, whereas silencing RICTOR rendered RICTOR-amplified cells markedly more resistant to mTORC1/2 inhibitors, demonstrating that RICTOR was the target in those cells." (PMID 29455662, 2018). "Moreover, analysis of the Cancer Genome Atlas (TCGA) database for RICTOR alteration demonstrated that RICTOR was amplified in around 13% (132/1016) of patients with lung cancers, including 10.3% in lung adenocarcinoma (53/515) and 15.8% (79/501) in squamous cell carcinoma." (PMID 29455662, 2018). "SFPQ, RTN4, HELLS, RICTOR, and LARP6 have high expression in lung cancer and other cancer cells and tissues." (PMID 37569873, 2023).